IL15 (interleukin 15)
Diseases named in the same sentence as IL15 in open-access papers (continued):
Sharing a sentence is not in itself a finding about the gene and the disease.
abortion (3 papers, 2021 to 2024). the ending of pregnancy by removing a fetus or embryo before it can survive outside the uterus. "IL-15 permits fetal loss in a model of lipopolysaccharide (LPS)-mediated abortion, in which low-dose LPS is given to pregnant dams post-implantation at E7.5." (PMID 34681751, 2021). "In the uterus of women with implantation failure, IL15 transcript was downregulated over twofold and trended toward marginal downregulation in women with recurrent spontaneous abortion." (PMID 34681751, 2021). "Nevertheless, when pretreated with LDN57444, an inhibitor of UCHL1, the expression of CXCL12, IL15 and TGF-β in normal DSCs was significantly decreased, as well as their ability to recruit and educate dNKs, which were similar to that of the abortion DSCs." (PMID 38769534, 2024). "Notably, CXCL12, IL15 and TGF-β were significantly downregulated in abortion DSCs, consequently leading to a substantial decrease in dNK percentage in the coculture assay with abortion DSCs." (PMID 38769534, 2024).
adult T cell leukemia (3 papers, 2014 to 2022). "This led to development of the phase 1 trial of IL-15 combined with alemtuzumab for patients with adult T cell leukemia (NCT02689453) as well as ongoing trials in chronic lymphocytic leukemia (NCT03759184, NCT03905135)." (PMID 35747794, 2022). "IL-15 was discovered in cells transformed by HTLV-1, the etiologic agent of adult T cell leukemia/lymphoma (ATL) and the human retrovirus that carries the Tax oncogene." (PMID 24416335, 2014).
Airway obstruction (3 papers, 2013 to 2025). Obstruction of conducting airways of the lung. "Similarly, a study conducted in smokers with computed tomography (CT) detected emphysema and without airway obstruction had demonstrated decreased plasma levels of cytokines including EGF, IL-8, IL-15, and IL-1RA than the smokers without CT detected emphysema." (PMID 25879453, 2015).
allergic rhinitis (3 papers, 2011 to 2024). Inflammation of the nasal mucous membranes caused by an IgE-mediated response to external allergens. "A report by A.E. El-Shazly demonstrated crosstalk between the human NK cell and eosinophil recruitment through the IL-15/IL-8 axis in the pathophysiology of allergic rhinitis and indicated the ability of IL-15 to upregulate IL-8 secretagogue activity through NK cells." (PMID 38790942, 2024). "This may indicate a role for IL-15 in the pathophysiology of allergic rhinitis late-phase reaction and the promotion of eosinophilic inflammation." (PMID 21765616, 2011).
aneurysm (3 papers, 2015 to 2023). Bulging or ballooning in an area of an artery secondary to arterial wall weakening. "By comparing the levels of 48 serum cytokines between low aneurysm growth risk and matched intermediate-high aneurysm growth risk patients, serum MCP-1, IL-15, and TNF-β were found to be significantly up-regulated in intermediate-high risk patients." (PMID 35783134, 2022). "Univariate logistic analysis demonstrated that high levels of IL-15 (OR, 3.10; 95% CI, 1.40–6.87; P = 0.005) and TNF-β (OR, 7.16; 95% CI, 2.67–19.18; P < 0.001) were risk factors for aneurysm progression." (PMID 35783134, 2022). "Multivariate logistic analysis indicated that high IL-15 (OR, 3.23; 95% CI, 1.47–7.12; P = 0.004) and TNF-β (OR, 8.30; 95% CI, 3.25–21.25; P < 0.001) levels were associated with aneurysm progression." (PMID 35783134, 2022). "Three cytokines, namely, interleukin-15 (IL-15), monocyte chemoattractant protein-1 (MCP-1), and tumor necrosis factors-β (TNF-β) were significantly increased in intermediate-high risk aneurysms compared with low risk aneurysms (P < 0.05, |log2 fold change| > 2)." (PMID 35783134, 2022). "Finally, our analysis indicated that high levels of IL-15 and TNF-β were correlated with aneurysm growth, serum IL-15 and TNF-β may act as potential biomarkers to identify aneurysm growth." (PMID 35783134, 2022).
atrial fibrillation (3 papers, 2020 to 2023). A disorder characterized by an electrocardiographic finding of a supraventricular arrhythmia characterized by the replacement of consistent P waves by rapid oscillations or fibrillatory waves that vary in size, shape and timing and are accompanied by an irregular ventricular response. "This is in line with prior studies showing elevated IL-6 and IL-15 in patients with atrial fibrillation." (PMID 37005652, 2023).
autism (3 papers, 2019 to 2023). Persistent deficits in social interaction and communication and interaction as well as a markedly restricted repertoire of activity and interest as well as repetitive patterns of behavior. "IL-15 is also involved in the activation of NK cell a finding previously seen in autism." (PMID 36830973, 2023). "Results showed that, following toll-like receptor stimulation, the autism group with GIS had higher levels of cytokines including IL-5, IL-15, and IL-17 compared to the autism group that were not presenting with GIS." (PMID 32532137, 2020).
autoimmune enteropathy (3 papers, 2014 to 2023). Severe-immune mediated enteropathy describes a variety of intestinal disorders that can range from a serious, early-onset systemic disease (IPEX) to a mild isolated gastrointestinal disease. "A study on transgenic mouse models with overexpression of IL-15 and consequent development of autoimmune enteropathy demonstrated that blocking antibody against IL-15 was capable of efficiently reversing the intestinal damage." (PMID 25705619, 2014).
autoimmune thyroid disease (3 papers, 2015 to 2023). Inflammatory disease of the thyroid gland due to autoimmune responses leading to lymphocytic infiltration of the gland. "Recently, in patients with autoimmune thyroiditis, increased IL-6 and IL-15 (another pro-inflammatory cytokine) were detected, likely due to increased proliferation and increased pro-inflammatory cytokine synthesis in T-helper 17 cells." (PMID 26100072, 2015).
Cerebral ischemia (3 papers, 2021 to 2025). Restriction of arterial blood supply to the brain associated with insufficient oxygenation to support the metabolic requirements of the tissue. "Transgenic mice expressing IL-15 with GFAP promoter exhibited worse neurological deficits following cerebral ischemia, while IL-15 knockdown in mice diminished the infarct size." (PMID 35008440, 2021). "Considering that factors upregulated in the acute period after brain ischemia commonly result in a detrimental outcome (such as IL-6, IL-15), we wondered whether increased cerebral FGF21 expression during the subacute and delay phases could play a positive role." (PMID 40021824, 2025).
cholangiocarcinoma (3 papers, 2021 to 2024). A carcinoma that arises from the intrahepatic biliary tree (intrahepatic cholangiocarcinoma) or from the junction, or adjacent to the junction, of the right and left hepatic ducts (hilar cholangiocarcinoma). "Also, IL-15 and IL-18 stimulated cells contained cytotoxicity against cholangiocarcinoma cells, suggesting that stimulated Vγ9Vδ2 T cells may provide a feasible therapy for cholangiocarcinoma." (PMID 38221530, 2024).
chordoma (3 papers, 2021 to 2024). Chordomas are rare malignant tumors arising from embryonic remnants of the notochord in axial skeleton. "Treatment of NK cells with an IL15 superagonist complex (N-803) increased their cytotoxicity against chordoma cells, which was further enhanced by treatment with N-601 and/or cetuximab." (PMID 35765577, 2021). "This suggests that strategies to increase NK cell proliferation and activation such as with interleukin-15 superagonism, or adoptive NK cell therapies may be beneficial for chordoma as previously shown in in vitro studies." (PMID 36338744, 2022). "One additional way to augment the NK and T cell coordinated response against CSCs, particularly in the setting of increased CSC NK ligand expression, could be to employ N803, an interleukin (IL)-15/IL-15-Rα superagonist (N803) previously shown by our group to enhance the killing of chordoma CSCs15." (PMID 38741774, 2024). "This is the first chordoma study demonstrating the efficacy of combinatorial immunotherapy with ADCC-mediating antibodies and an IL15 superagonist complex in an NK cell–based treatment paradigm." (PMID 35765577, 2021).
chromophobe renal cell carcinoma (3 papers, 2022 to 2025). Chromophobe renal cell carcinoma is a rare subtype of renal cell carcinoma, originating from the intercalating cells of the collecting ducts and macroscopically manifesting as a well-circumscribed, highly lobulated, solid tumor that is usually diagnosed at an early stage. "In chromophobe renal cell carcinoma (chRCC), cytotoxicity against tumor cells mediated by ILC1s was shown to be dependent on the production of IL-15 by the tumor cells." (PMID 35962192, 2022). "Similarly, in chromophobe renal cell carcinoma (chRCC), high infiltration of granzyme A (GzmA)-expressing intraepithelial ILC1s was positively correlated with patient survival, with IL-15 promoting both their expansion and cytotoxicity." (PMID 40963622, 2025).
chronic hepatitis B (3 papers, 2011 to 2023). "IL-15 has been associated with multiple inflammatory diseases, is up-regulated following liver injury and is increased in patients with chronic hepatitis B and C infection." (PMID 21876747, 2011). "Control, inactive HBV carriers, HBV recovered, and chronic hepatitis B patients, several comparative analysis shows that IL-15 was significantly down-regulated in HBV-infected groups (inactive carriers, P=0.005; and chronic HBV infected, P=0.025) compared with uninfected control." (PMID 36742132, 2023).
chronic kidney disease (3 papers, 2019 to 2024). Impairment of the renal function secondary to chronic kidney damage persisting for three or more months. "We found increased levels of IL-6, IL-8, CD40, PDL-1, FGF-23, IL-15-RA, TGF-a, and CCL25 that persist at two months after LTA in IKF patients, consistent with current concepts of inflammation as a crucial pathophysiological mechanism in the development of chronic kidney disease." (PMID 39440014, 2024). "Taken together, these data suggest that IL-15 reduction, as observed for the antifibrotic factors, such as BMP-7 and HGF, may be a critical event in renal fibrogenesis and in acute and chronic kidney diseases." (PMID 34769128, 2021).
chronic pancreatitis (3 papers, 2021 to 2024). A chronic inflammatory process causing damage and fibrosis of the pancreatic parenchyma. "NK cells, synergistically with IL-15, can inhibit fibrosis in chronic pancreatitis by suppressing alveolar cell atrophy, preventing tissue collagen accumulation around blood vessels, and down-regulate pro-fibrotic genes." (PMID 39309440, 2024). "Moreover, the pharmacological delivery of IL-15 reverses fibrosis in models of chronic pancreatitis by promoting the induction of INF-γ, producing NK and NKT cells, and reducing TGF-β levels." (PMID 34769128, 2021).
colon adenocarcinoma (3 papers, 2022 to 2025). "Radiation exposure markedly increases PIEZO2 expression in colon adenocarcinoma cells, leading to suppression of interleukin-15 (IL-15) production via inhibition of the JAK2/STAT1/IRF-1 axis." (PMID 41327436, 2025).
colorectal tumor (3 papers, 2020 to 2025). "Overall, plant-produced Pembrolizumab-IL-15Rα-IL-15 fusion protein showed effective anti-tumor activity in mouse models induced with colorectal tumor." (PMID 39808627, 2025). "An ongoing multicenter phase IIb clinical trial (NCT05419011) aims to evaluate whether the combination of trivalent adenovirus-5 (Tri-Ad5) vaccines and the IL-15 superagonist nogapendekin alfa inbakicept (N-803) can reduce the incidence of colorectal neoplasms in patients with LS." (PMID 41463230, 2025). "The potential of this combination regimen is not just limited to PDAC, since IL‐15 and CD40 agonist therapy has been tested by others in mice bearing established CT26 and MC38 colorectal tumors." (PMID 32821382, 2020).
cutaneous melanoma (3 papers, 2022 to 2024). A primary melanoma arising from atypical melanocytes in the skin. "On the other hand, a high expression of IL-15 was associated with the prediction of a positive survival outcome in different cancer patients, including those with skin melanoma." (PMID 38164270, 2024). "At first, IL-15 mRNA expression and protein levels were found to be significantly down-modulated in 12 different tumors, including skin melanoma, compared with normal tissues." (PMID 38164270, 2024). "In pathologic conditions, in cutaneous melanomas, IL-15+ tumor cells displayed a broad distribution that intensifies at different stages, becoming almost total in metastatic samples." (PMID 37334356, 2023).
delirium (3 papers, 2013 to 2025). A disorder characterized by confusion; inattentiveness; disorientation; illusions; hallucinations; agitation; and in some instances autonomic nervous system overactivity. "In this descriptive study it is surprising to find that lower levels of IL-6 as well as IL-15 were associated with the development of postoperative delirium." (PMID 24093540, 2013). "Despite the limited power of this exploratory study, we found significantly lower levels of Flt-3L, IL-1ra, and IL-6 and distinct trends for lower levels of IL-15 and higher levels of IP-10 in CSF of patients with postoperative delirium." (PMID 24093540, 2013).
encephalitis (3 papers, 2022 to 2025). An acute inflammatory process affecting the brain parenchyma. "Of these, the negative association of IL-15 with Qalb is a novel finding as, to our knowledge, IL-15 has not been studied in viral encephalitis before, but it can be interpreted in a framework of the upregulated TNFα-dependent response." (PMID 40003967, 2025). "A clinical study found that the serum levels of eotaxin, IFN- γ, IL-15, IL-6, IP-10, and TNF-α in the confirmed encephalitis patients were elevated remarkably before clinical deterioration, which might be related to a potential association with the development of encephalitis." (PMID 35782112, 2022). "It was also noted that the levels of serum eotaxin, IFN-γ, IL-15, IL-6, IP-10, and TNF-α were significantly elevated before clinical deterioration in the confirmed encephalitis patient, suggesting the roles of these cytokines in the development of encephalitis." (PMID 35782112, 2022). "In addition, blood eosinophil leukocyte chemotactic factor, IFN-γ, IL-15, IL-6, interferon gamma-induced protein-10, and tumor necrosis factor-α were significantly elevated before disease deterioration in a non-fatal encephalitis SFTS patient, which may be due to encephalitis development." (PMID 36406394, 2022).
enteropathy (3 papers, 2018 to 2022). "Administration of IL-15 and IL-15 TG2-NiMOS showed an improvement in inflammatory condition in mice Poly (I:C)-induced enteropathy, suggesting another possible approach to treat the disease." (PMID 35457155, 2022). "In IL-15-overexpressing transgenic mice enteropathy models, IL-15 blockade with anti-IL-15 antibody was shown to reverse intestinal damage." (PMID 30050538, 2018). "Microscopic examination of H&E stained jejunum biopsy tissues collected from studied macaques prior, during, and after the anti-IL-15 treatment revealed enteropathy with subsequent amelioration upon anti-IL-15 treatment." (PMID 30050538, 2018). "We previously reported that P31-43 induces additional pro-inflammatory effects on Caco-2 cells, namely NLRP3 inflammasome activation and NF-κB p65 translocation into the nucleus with consequent increased IL-1β production and upregulation of IL-15, a known mediator of the gliadin-induced enteropathy." (PMID 30981209, 2019). "For the anti-IL-15 treatment phase, the six GSE macaques were divided into two groups of 3 based on severity of enteropathy; mild (group 1) and moderate (group 2)." (PMID 30050538, 2018). "For now, we can conclude that the effects of human anti-IL-15 therapy in GSE macaques are consistent with those produced by other anti-IL-15 antibodies, specifically reduced numbers of peripheral NK cells, IELs and enteropathy improvement." (PMID 30050538, 2018).
H1N1 virus infection (3 papers, 2010 to 2021). "Another study in critically ill patients with ARDS caused by 2009 H1N1 virus infection has shown that the hallmarks of disease severity were elevated levels of IL-6, IL-15, IL-8 and TNF-α." (PMID 22235288, 2012). "In our critically ill patients with nvA(H1N1) virus infection we found increased levels of some cytokines: IP-10, TNFα, IL-15, IL-12, IL-6, IL-8 and IL-9." (PMID 21062445, 2010). "In our critically ill patients with novel influenza A(H1N1) virus infection, the hallmarks of the severity of disease were IL-6, IL-15, IL-8 and TNFα." (PMID 21062445, 2010).
hantavirus infection (3 papers, 2014 to 2019). "Corroborating this notion, in vitro, hantavirus infection was found to induce transcription of IL‐15 and IL‐15Rα mRNAs and cause increased IL‐15 and IL‐15Rα cell surface expression." (PMID 30663801, 2019). "In hantavirus infection, however, IL-15-mediated activation of NK cells was shown to circumvent self-tolerance mechanisms leading to targeting of uninfected endothelial cells, demonstrating a potential role in pathogenesis." (PMID 30557313, 2018).
injury (3 papers, 2013 to 2020). Damage inflicted on the body as the direct or indirect result of an external force, with or without disruption of structural continuity. "IL-15 can regulate inflammatory cell infiltration locally and in the peripheral nervous system after nerve injury, linking inflammation and pain generation." (PMID 32793194, 2020). "Pro-inflammatory cytokine IL-15 regulates neuro-immune responses by regulating T-cell and macrophage infiltration and activation after nerve injury." (PMID 23630573, 2013).
ischemia (3 papers, 2014 to 2023). A hypoperfusion of the BLOOD through an organ or tissue caused by a PATHOLOGIC CONSTRICTION or obstruction of its BLOOD VESSELS, or an absence of BLOOD CIRCULATION. "IL-15 is mostly produced by monocytes and its blockade reduces brain injury after ischemia." (PMID 36803375, 2023). "Together, IL-15 and IL-8 elevation can increase local inflammation in the brain, leading to vasculitis in subarachnoid spaces; interfering with blood supply; promoting ischemia, necrosis, and infarction of the brain tissue; and potentially leading to increased risk of death." (PMID 38152404, 2023). "Mild positivity of immunoreaction (tryptase, CD15, IL-1β, IL-6, IL-8, TNF-α) and stronger reactivity for IL-15, MCP-1 in areas where depletion of cellular antigens (myoglobin and cardiac troponin) is detectable within 30 – 40 minutes from ischemia." (PMID 24989171, 2014).
latent infection (3 papers, 2018 to 2025). "CCL19, CCL21, IL-7, and IL-15 are known to promote latent infection in resting CD4+ T-cells." (PMID 29997630, 2018). "MIs are recruited as CX3CR1+CD8+ T cells by CX3CL1, which is released from inflamed blood vessels, to sites of latent infection and expand on non-hematopoietic cells in IL-15-rich niches." (PMID 40028277, 2025).
liver disease (3 papers, 2018 to 2023). "Interleukin 15 from hepatic monocytes was found to be an inducer of bystander activation of T cells, which is associated with progression of liver disease in the participants with T2D." (PMID 37735474, 2023). "Higher levels of IL-15 subsequently exaggerates severity in our murine model of antigen-driven liver disease." (PMID 29449577, 2018). "Collectively, these data suggest that hepatic T cells with senescence and IL-15-producing nonclassical monocytes may be involved in the progression of liver disease in patients with T2D." (PMID 37735474, 2023).